CD44 (CD44 molecule (IN blood group))
Diseases named in the same sentence as CD44 in open-access papers (continued):
Sharing a sentence is not in itself a finding about the gene and the disease.
endometriosis (continued). "A recent in vivo study examining CD44 expression (a protein that seems to play a role on cell adhesion) in endometrial cells of women with endometriosis showed a significant decrease after administration of oral vit D." (PMID 36578019, 2022). "The overexpression of CD44 variants activates a diversity of downstream pathways, including CD44/EGFR/PI3K-Akt and CD44/NF-κB, thus characterizing endometriosis with dominant migration and invasiveness." (PMID 36499654, 2022). "Some of these studies demonstrated that both CD44 and E-cadherin expressions were higher in the eutopic and/or ectopic endometrial tissues of women with endometriosis than in control endometrial tissues." (PMID 33218351, 2020). "Through interactions between PMCs and ESCs in this co-culture system, several endometriosis-related genes including CD44, ERK, CSF-1, and c-Met were upregulated in both PMCs and ESCs." (PMID 31636643, 2019). "Integrins, syndecans, cadherins, CD44, and CD44’s binding partner hyaluronan have been studied extensively in endometrium and in endometriosis." (PMID 31717614, 2019). "Given the background on HA and 4-MU, and the potential involvement of CD44-HA interaction in the pathogenesis of endometriosis, the aim of the present study was to analyze for the first time the effects of 4-MU on endometriosis-related angiogenesis." (PMID 27018976, 2016). "Altered glandular CD44 expression in the receptive phase likely reflects endometriosis-associated epithelial adhesion changes rather than a phase-specific marker of functional receptivity." (PMID 42010698, 2026). "This research provides insight into a strong relationship between OPN, CD44, and endometriosis." (PMID 37509675, 2023). "In the pathophysiology of endometriosis, CD44 and OPN seem to both play some important role by influencing a multitude of underlying processes that result in the appearance and growth of endometriotic ectopic tissue, such as adhesion, invasion, inflammation, angiogenesis, and stem cell activity." (PMID 37509675, 2023). "The effects of progestins on CD44 expression in endometriosis may depend on various factors, including the specific dosage, treatment duration, and patient’s individual characteristics." (PMID 37509675, 2023). "Furthermore, the levels of cell adhesion molecules such as ICAM-1, VCAM-1, and CD44, which modulate cell–matrix and cell–cell attachments, are increased in the serum, peritoneal fluid, and endometrium of patients with endometriosis." (PMID 35409294, 2022). "Moreover, CD44 glycoproteins are critical mediators of tumorigenesis, endometriosis, and embryo epithelial interaction." (PMID 36527033, 2022). "The results suggest that CD44 expression in pDCs may be involved in lesion survival in this surgically induced murine model of endometriosis." (PMID 33807420, 2021). "High expressions of FB receptors associated with pro-fibrosis and adhesion, such as FGFR1, FGFR4, ICAM, and CD44, were activated by ligands in immune cells, suggesting that alternate endometriosis immune cells played an important role in promoting lesion development." (PMID 34233737, 2021). "Higher follicular MIP-1α and CD44(v6) were found to correlate with polycystic ovary syndrome, IL-23, INF-γ, and TNF-α with endometriosis, higher CD44(v6) but lower IL-β and INF-α correlated with tubal factor infertility, and lower levels of IL-18 and CD44(v6) characterized unexplained infertility." (PMID 22007253, 2012). "Interestingly, in this later study the effects of 1,25(OH)2D on CD44 were associated with enhanced expression of β‐catenin, suggesting that the mechanism for vitamin D regulation of CD44 in endometriosis may be different to that observed for cancers." (PMID 39739404, 2025).
endometriosis (continued). "It is also worth mentioning that CD44 is involved in the self-renewal and differentiation of stem cells, with its altered expression and signaling suspected to influence the behavior of endometrial stem cells, thereby contributing to the pathogenesis of endometriosis." (PMID 37509675, 2023). "Nevertheless, it remains unclear how CD44 interacts with EMT in patients with endometriosis." (PMID 36499654, 2022). "However, the interaction between OPN and CD44 in endometriosis remains poorly understood." (PMID 36499654, 2022). "Moreover, CD44 expression was negatively correlated with the presence of peritoneal endometriotic lesions (p = 0.0304), while E-cadherin expression was negatively correlated with the presence of deep infiltrating endometriosis (p = 0.0445)." (PMID 33218351, 2020). "Moreover, we also found that CD44 expression was negatively correlated with the presence of peritoneal endometriotic lesions, whileE-cadherine expression was negatively correlated with the presence of deep infiltrating endometriosis." (PMID 33218351, 2020). "Additionally, CD44 expression was negatively correlated with the presence of peritoneal endometriotic lesions, and E-cadherin expression was negatively correlated with the presence of deep infiltrating endometriosis." (PMID 33218351, 2020). "Finally, expression of the transmembrane adhesion molecule and stem cell marker CD44 is dysregulated in endometriosis, as exemplified by the correlation of high levels of soluble CD44 in the serum and peritoneal fluid of endometriosis patients with the severity of the disease." (PMID 31717614, 2019). "Moreover, CD44-HA interaction also mediates proliferation, inflammation and angiogenesis, which represent fundamental processes in the formation of new endometriotic lesions and, thus, potential therapeutic targets for the treatment of endometriosis." (PMID 27018976, 2016). "This study aimed to evaluate compartment-specific immunohistochemical expression patterns of HOXA-10, HOXA-11, CD44, β1 integrin, ECM-1, and focal adhesion kinase (FAK) in women with endometriosis-related implantation failure." (PMID 42010698, 2026). "As reduced CD44 expression has been reported in the stroma cells of endometriosis lesions, we tested the effects of MLLT11 knockdown on CD44 expression and WNT pathway activity." (PMID 38203610, 2023). "In this study, we investigated CD44 and OPN, two molecules thought to be important in the onset and progression of endometriosis, to determine if they exhibit any changes in response to progestin therapy." (PMID 37509675, 2023). "This study set out to assess the involvement of CD44 and OPN in endometriosis, as well as their potential use in novel treatment strategies for the disease." (PMID 37509675, 2023). "CD44 expression and the interaction between CD44 and OPN isoforms in the pathogenesis of endometriosis have been examined in several studies, but the results have been inconsistent." (PMID 36499654, 2022). "Notably, and CD91+ macrophages and CD44+ monocytes appear to have different dynamics throughout the cycle in controls and endometriosis patients, as well as different proportions between the two groups, suggesting that they may be key components for the pathophysiology of the disease." (PMID 35421980, 2022). "There were also genes methylated in endometriosis, mainly PYCARD, RARB, RB1, IL2, CFTR, CD44 and CDH13; and ENOC—MLH3, BRCA1, CADM1, PAH." (PMID 36612107, 2022). "For example, higher follicular MIP-1α (CCL3) and CD44 were correlated with polycystic ovary syndrome and IL-23, IFN-γ, and TNF-α correlated with endometriosis." (PMID 34868029, 2021). "Significant differences were encountered between endometriosis and EC in case of five analytes, of which all were increased: ALDH1A (p = 0.019), CA9 (p = 0.031), CD44 (p = 0.010), hepsin (p = 0.007), midkine (p < 0.001)." (PMID 31035965, 2019).
endometriosis (continued). "Future investigations are warranted to delineate the roles of CD44, HASs, hyaluronidases and ST2 in the development of endometriosis." (PMID 31239500, 2019). "Furthermore, in 3D spheroid cultures of endometriosis, an increased co-expression of the CSC surface markers CD44 and CD133 was observed, with increased tumor invasion in the ‘high-risk’ group." (PMID 39684461, 2024). "All cases of endometriosis, with and without treatment, showed an intensely positive reaction for CD44." (PMID 37509675, 2023). "They evaluated the levels of the CD44 mRNA in the endometrial stromal cells of women with and without endometriosis using reverse transcription-polymerase chain reaction (rPCR), and the serum CD44 levels in the same women using the western blot technique." (PMID 37509675, 2023). "There is a lack of data concerning the levels of OPN in women with endometriosis and the levels of CD44 and OPN in endometriotic ectopic tissue from endometriosis specimens." (PMID 37509675, 2023). "We found that women with endometriosis who were not receiving progestin therapy had increased levels of CD44 expression in both stromal and epithelial compartments." (PMID 37509675, 2023). "Moreover, it has been found that overexpression of HOXA11-AS increases the membrane levels of CD44 and decreases the expression of matrix metalloproteinase-2, MMP-9, and vascular endothelial growth factors that are dysregulated in endometriosis." (PMID 35054341, 2022). "Alternatively, other receptors capable of binding with MIF-CD74 complexes, such as CD44 could also contribute to MIF signaling in endometriosis." (PMID 35885004, 2022). "Interestingly, the opposite pattern was observed in CD44+ classical monocytes and CD91+ macrophages from women with endometriosis." (PMID 35421980, 2022). "The expression of CD44 and ICAM-1 in ectopic endometrial cells may promote adhesion and enhance endometriosis pathogenesis." (PMID 33807420, 2021). "Concentration of seven analytes (ALDH1A, CA9, CD44, hepsin, midkine, TGM2, and kallikrein-6) differed in endometriosis samples as compared to control samples and levels of five markers (ALDH1A, CA9, CD44, hepsin, and midkine) were different between endometriosis and EC samples." (PMID 31035965, 2019). "CD44 is a mesenchymal stem cell (MSC) marker; the rare epithelial progenitors and MSCs are likely responsible for regenerative capacity that plays a critical role in the development of endometriosis and endometrial cancer." (PMID 20374665, 2010). "Moreover, cyto-hub gene analysis revealed that CSNK2A1, CSNK2A2, TOP1, PRKACA, RBM39 (plasma), ALB, ACTB, GAPDH, FN1, APOA1 (serum), S100-A9, CXCL1, IL1RN, CSTA, S100-A8 (menstrual blood) and THBS1, ALB, CD44, ANXA2, and LUM (urine) were the top 5 proteins expressed in women with endometriosis." (PMID 39061077, 2024). "It was also found that a regression model consisting of CD44 and TGM2 discriminated endometriosis from control samples with high accuracy (AUC 0.98, 95% CI 0.85–1.00, p < 0.001), however this result needs to be considered as preliminary due to the small number of endometriosis samples." (PMID 31035965, 2019).
brain tumor (34 papers, 1994 to 2025). "The HA receptor CD44 has been linked to brain tumour progression; hence we chose CD44 as a marker for our MB cell–HA interaction." (PMID 33206391, 2021). "In brain tumors, CD44 expression is associated with increased tumor initiation and progression." (PMID 29259986, 2017). "CD44 is enrolled in various functions in the nervous system, including axon guidance, synaptic transmission, and brain tumor development." (PMID 40106490, 2025). "A high level of CD44 in a tumor correlates with a poor survival prognosis for patients with various cancers, including brain tumors, so it is often considered as a marker of tumor stem cells, although this assumption is questioned by some researchers." (PMID 38672482, 2024). "CD44 knockdown inhibited GSCs’ migration and invasion both in vitro and in vivo; mouse brain tumors generated from CD44-knockdown GSCs were less invasive and mice survived significantly longer than control mice." (PMID 37108208, 2023). "The binding of CD44 to osteopontin, which is also abundant in brain tumors, leads to enhanced CD44 cleavage and the released CD44-ICD enhances the expression of hypoxia-inducible factor HIF-2α, promoting a hypoxic response in necrotic and perivascular areas." (PMID 35954411, 2022). "CD44 expression was seen to be significantly enhanced in primary brain tumors as compared to normal brain tissues." (PMID 36231019, 2022). "This is true for Notch receptors and canonical Notch ligands such as Dll1 and Jag1 —some of the closest relatives to DLK1—and for proteins involved in brain tumor and neural stem cell maintenance like CD44 and p75NTR." (PMID 32205867, 2020). "Other ECM components, such as hyaluronic acid, the adhesion molecule CD44 and tenascins interact with versican and stimulate brain tumor invasion." (PMID 31803736, 2019). "The level and pattern of CD44 expression in normal brain tissues and brain tumor tissues was examined by immunohistochemical staining." (PMID 28279210, 2017). "When compared with normal brain tissues, CD44 expression was significantly overexpressed in brain tumor tissues (p < 0.001)." (PMID 28279210, 2017). "Several studies have demonstrated the correlation between high CD44 expression and poor prognosis in patients with brain tumour." (PMID 25999819, 2015). "In our opinion, the identified negative association between Cd44 and Sox2 will require further investigation because it indirectly indicates the presence of several types of cells with stem characteristics in brain tumors." (PMID 38672482, 2024). "Next, we evaluate whether the high expressions of collagen type I receptors (ITGAV, ITGB8, SDC1, SDC4, and CD44) in tumor tissues, i.e., tumor receptors, are related with the prognosis of patients with brain tumor." (PMID 37479733, 2023). "Accordingly, CD44 showed higher expression in higher-grade brain tumors." (PMID 29259986, 2017). "To address this issue, we investigated CD44 expression patterns in brain metastases (BMTs) spread from more than ten organs and five types of primary brain tumours (PBTs) by Northern blot, reverse transcription-polymerase chain reaction (RT-PCR) and immunocytochemical analysis." (PMID 7541233, 1995). "Thus not only MUC 2-63 but also other anti-CD44 monoclonal antibodies should prove useful in imaging and, perhaps, therapy of brain tumours." (PMID 7524600, 1994). "In addition, it has been found that a subset of human GBM cases showed high expression of CD44 in brain tumour stem-like cells (BTSC), and that the growth of these tumours might depend on CD44v6/AKT signaling pathway." (PMID 25999819, 2015). "The co-expression of HER family members, with EGFRvIII, CD44, and CD109 was examined in the tumour specimens from patients with a brain tumour." (PMID 40227788, 2025).
brain tumor (continued). "Following the determination of the expression of HER family members, EGFRvIII, CD44, and CD109 in tumour specimens from patients with a brain tumour, a Fishers Exact correlation test was performed to find any association between the expression of these receptors and the clinicopathological features." (PMID 40227788, 2025). "Overall, it appears that both the overexpression and lack of expression of CD44 might be involved in the development and invasiveness of various brain tumour types." (PMID 25999819, 2015).
endometrial cancer (31 papers, 1998 to 2025). Primary or metastatic malignant neoplasm involving the endometrium (mucous membrane that lines the endometrial cavity). "Expression of CD44 has been reported to be lower in endometrial cancer than in normal tissue and loss of CD44 associated with lymphovascular space invasion." (PMID 39888143, 2025). "Previous studies have reported high expression of CD44 to associate with worse outcome in several cancers, including a smaller cohort of endometrial cancer patients (n = 113)." (PMID 39888143, 2025). "Since all the cancers detected, except for the endometrial cancer and malignant phyllodes tumor, are associated with tobacco use, the role of CD44 as an early detection tool for tobacco users can extend beyond OOPSCC." (PMID 39030509, 2024). "In the context of endometrial cancer (EC) patients classified as high-intermediate-risk and high-risk, it is pertinent to discuss the influence of varying co-expression patterns of CD44 & CD133—low, mixed, and high—on the efficacy of adjuvant therapy." (PMID 38706601, 2024). "Because this is usually accompanied by a significant increase in the serum levels of hyaluronan in endometrial cancer patients, it has been proposed that the adhesion signaling associated with CD44 is involved in the progression of endometrial cancer." (PMID 26849234, 2016). "We investigated the expression of CD44 isoforms containing variant exons v3, v5, v6 and v7-8 in 156 human endometrium cancer specimens by means of immunohistochemistry." (PMID 9569051, 1998). "High expression of CD44 alone predicts poor overall survival, and simultaneous expression of CD44 and Aldehyde dehydrogenase 1 is linked to extremely unfavorable overall survival among endometrial cancer patients." (PMID 33303029, 2020). "Both disease‐specific and progression‐free survival was significantly higher for endometrial cancer patients with high expression of CD44." (PMID 39888143, 2025). "Further, CD133/CD44+ endometrial cancer cells expressed the pluripotency markers Sox-2, Nanog, and Oct4 or other stemness-related genes with intense clonogenic ability." (PMID 40804837, 2025). "CD44 is a transmembrane adhesion molecule suggested to be a useful marker of CSCs in endometrial cancer." (PMID 38539419, 2024). "In endometrial cancer, specific cell surface markers, including CD44-antigen (CD44) and prominin-1 (CD133), have been identified as surrogate markers for CSCs." (PMID 38539419, 2024). "We used Western blotting to detect the downregulated expression of WTAP in endometrial cancer stem cells compared to that in Ishikawa cells, while other stem cell indicators, such as CD44, CD133, SOX2 and NANOG, were upregulated in ECSCs." (PMID 39044249, 2024). "The purpose of this study was to investigate the correlation between stemness markers (CD44 and CD133) and clinical pathological features, and to further explore the prognostic value of co-expression of CD44 & CD133 in endometrial cancer (EC)." (PMID 38706601, 2024). "CD133/CD44+ endometrial cancer cells were able to form tumor spheres, showed enhanced chemoresistance and were able to initiate tumor formation with the same phenotype as the parental tumor when transplanted into immunodeficient mice." (PMID 35328833, 2022). "Further, CD133/CD44+ cells isolated from endometrial cancers expressed the pluripotency markers Myc, Sox-2, Nanog and Oct4 as well as other stemness-related genes such as Nestin and showed enhanced clonogenic ability and sphere formation." (PMID 35328833, 2022). "Endometrial carcinoma-derived stem-like cells (ECSCs) are commonly identified using specific cell surface markers, such as CD44-antigen (CD44) and Prominin-1 (CD133), as their expression is associated with tumorigenicity, invasiveness and metastasis." (PMID 35269569, 2022).